RNU6-267P (RNA, U6 small nuclear 267, pseudogene)
Gene: Small nuclear RNA gene on chromosome 7 (143,754,628 to 143,754,730, reverse strand). Ensembl gene ENSG00000252523.
Homologues: Orthologues: chimpanzee U6 (99% identical), macaque U6 (94% identical), macaque U6 (93% identical), macaque U6 (92% identical), dog U6 (72% identical), rabbit U6 (72% identical), pig U6 (68% identical), mouse Gm25619 (66% identical), mouse Gm26072 (66% identical), mouse Gm26271 (66% identical), guinea pig U6 (64% identical), rat U6 (61% identical), and 2 more. Paralogues in human: RNU6-162P (99% identical), RNU6-144P (79% identical), RNU6-16P (79% identical), RNU6-46P (79% identical), RNU6-480P (79% identical), RNU6-1316P (78% identical), RNU6-310P (78% identical), RNU6-434P (78% identical), RNU6-1 (77% identical), RNU6-10P (77% identical), RNU6-116P (77% identical), RNU6-11P (77% identical), and 1285 more.